CNOT10 (CCR4-NOT transcription complex subunit 10)
Description:
Component of the CCR4-NOT complex which is one of the major cellular mRNA deadenylases and is linked to various cellular processes including bulk mRNA degradation, miRNA-mediated repression, translational repression during translational initiation and general transcription regulation. Additional complex functions may be a consequence of its influence on mRNA expression. Is not required for association of CNOT7 to the CCR4-NOT complex.
Synonyms: FLJ12890; FLJ13165
Tractability: PROTAC: ubiquitination databases record sites on it; its protein half-life has been measured.
Gene: Protein-coding gene on chromosome 3 (32,685,139 to 32,773,875, forward strand). Ensembl gene ENSG00000182973.
Subcellular location: Cytoplasm; Nucleus
Subcellular location (Human Protein Atlas): Centrosome; Nucleoplasm; Cytosol
Pathways (Reactome):
Developmental Biology: M-decay: degradation of maternal mRNAs by maternally stored factors
Metabolism of RNA: Deadenylation of mRNA
Gene Ontology:
Molecular function: protein binding
Biological process: mRNA catabolic process; negative regulation of translation; nuclear-transcribed mRNA poly(A) tail shortening
Cellular component: CCR4-NOT complex; membrane; cytosol; cytoplasm; nucleus
Genetic constraint (gnomAD): Loss-of-function variants: 13 observed, 51.09 expected, observed/expected ratio (o/e) 0.25, 90% interval 0.17 to 0.41. The upper end of that interval is the gene's LOEUF score, 0.41, which puts it in group 1 of 6, group 1 being the genes least tolerant of losing a copy. Missense variants: 494 observed, 575.04 expected, observed/expected ratio (o/e) 0.86, 90% interval 0.8 to 0.93. Synonymous variants: 200 observed, 203.79 expected, observed/expected ratio (o/e) 0.98, 90% interval 0.87 to 1.1.
Homologues: Orthologues: macaque CNOT10 (99% identical), chimpanzee CNOT10 (99% identical), pig CNOT10 (97% identical), dog CNOT10 (97% identical), guinea pig CNOT10 (96% identical), mouse Cnot10 (96% identical), rabbit CNOT10 (96% identical), rat Cnot10 (95% identical), tropical clawed frog cnot10 (84% identical), zebrafish cnot10 (66% identical), Drosophila melanogaster Not10 (23% identical).
Diseases named in the same sentence as CNOT10 in open-access papers:
CNOT10 is named in the same sentence as 2 diseases in open-access papers, as found by Europe PMC text mining. Sharing a sentence is not in itself a finding about the gene and the disease. The quoted sentences say what the papers report.
Hypertension (2 papers, 2020 to 2023). The presence of chronic increased pressure in the systemic arterial system. "The CNOT10 gene was probably associated with left ventricular remodeling in hypertension by bioinformatics-based analysis." (PMID 36869404, 2023).
CNOT10 also shares sentences with these, for which no sentence is quoted: leukemia (1 paper).